TF (transferrin)
Description:
Transferrins are iron binding transport proteins which can bind two Fe(3+) ions in association with the binding of an anion, usually bicarbonate. It is responsible for the transport of iron from sites of absorption and heme degradation to those of storage and utilization. Serum transferrin may also have a further role in stimulating cell proliferation. (Microbial infection) Serves as an iron source for Neisseria species, which capture the protein and extract its iron for their own use. (Microbial infection) Serves as an iron source for parasite T.brucei (strain 427), which capture TF via its own transferrin receptor ESAG6:ESAG7 and extract its iron for its own use.
Synonyms: PRO1557; PRO2086; HEL-S-71p; TFQTL1
Tractability: Small molecule: a structure with a bound ligand is known; it has a high-quality binding pocket. Antibody: its Gene Ontology location is reachable by antibodies, with high confidence; UniProt places it where antibodies can reach, with medium confidence; UniProt predicts a signal peptide or a membrane-spanning region. PROTAC: its protein half-life has been measured.
Target class: Secreted protein
Safety:
Unwanted effects reported when the protein is acted on. In parentheses: how it was acted on, where the effect was seen, and who reports it.
N/A, Breast Cancer (activation; source: AOP-Wiki)
Gene: Protein-coding gene on chromosome 3 (133,746,040 to 133,796,641, forward strand). Ensembl gene ENSG00000091513.
Subcellular location: Secreted
Pathways (Reactome):
Metabolism of proteins: Post-translational protein phosphorylation; Regulation of Insulin-like Growth Factor (IGF) transport and uptake by Insulin-like Growth Factor Binding Proteins (IGFBPs)
Transport of small molecules: Iron uptake and transport; Transferrin endocytosis and recycling
Vesicle-mediated transport: Cargo recognition for clathrin-mediated endocytosis; Clathrin-mediated endocytosis
Hemostasis: Platelet degranulation
Gene Ontology:
Molecular function: enzyme binding; ferrous iron binding; iron chaperone activity; protein binding; transferrin receptor binding; transmembrane transporter binding; ferric iron binding; iron ion binding
Biological process: cell surface receptor signaling pathway; cellular response to iron ion; intracellular iron ion homeostasis; iron ion transport; multicellular organismal-level iron ion homeostasis; positive regulation of proteasomal ubiquitin-dependent protein catabolic process; positive regulation of receptor-mediated endocytosis; antibacterial humoral response; regulation of protein stability; osteoclast differentiation
Cellular component: apical plasma membrane; basal part of cell; basal plasma membrane; blood microparticle; cell surface; clathrin-coated pit; cytoplasmic vesicle; early endosome; endocytic vesicle; extracellular exosome; extracellular region; HFE-transferrin receptor complex; late endosome; perinuclear region of cytoplasm; recycling endosome; vesicle; clathrin-coated endocytic vesicle membrane; endoplasmic reticulum lumen; endosome membrane; plasma membrane; secretory granule lumen; endosome; membrane
Genetic constraint (gnomAD): Loss-of-function variants: 56 observed, 83.84 expected, observed/expected ratio (o/e) 0.67, 90% interval 0.54 to 0.83. The upper end of that interval is the gene's LOEUF score, 0.83, which puts it in group 3 of 6, group 1 being the genes least tolerant of losing a copy. Missense variants: 733 observed, 902.1 expected, observed/expected ratio (o/e) 0.81, 90% interval 0.76 to 0.86. Synonymous variants: 332 observed, 346.25 expected, observed/expected ratio (o/e) 0.96, 90% interval 0.88 to 1.05.
Gene-disease validity (ClinGen):
ClinGen rates the evidence that TF causes each of these diseases.
atransferrinemia (autosomal recessive): Moderate. Congenital atransferrinemia is a very rare hematologic disease caused by a transferrin (TF) deficiency and characterized by microcytic, hypochromic anemia (manifesting with pallor, fatigue and growth retardation) and iron overload, and that can be fatal if left untreated.
Homologues: Orthologues: chimpanzee TF (99% identical), macaque TF (92% identical), mouse Trf (73% identical), pig TF (70% identical), zebrafish sxph (36% identical), tropical clawed frog depdc5 (33% identical). Paralogues in human: LTF (61% identical), MELTF (41% identical), SRPRB (4% identical).
Diseases named in the same sentence as TF in open-access papers:
TF is named in the same sentence as 688 diseases in open-access papers, as found by Europe PMC text mining. Sharing a sentence is not in itself a finding about the gene and the disease. The quoted sentences say what the papers report.
iron deficiency (543 papers, 2001 to 2026). "Lab analysis showed iron deficiency anemia (hemoglobin (Hb) 7.2 g/dL, normocytic and normochromic, serum iron 54.9 μg/dL, ferritin 146 ng/mL, and transferrin saturation (TSAT) 17%; serum folate 5.6 ng/mL and vitamin B12 1229 pg/mL)." (PMID 42077715, 2026). "Two exposure groups were defined: absolute iron deficiency (serum ferritin < 30 ug/L) and functional iron deficiency (transferrin saturation < 20% and serum ferritin ≥ 30 ug/L)." (PMID 41952150, 2026). "The average transferrin saturation two months after surgery was 0.21 ± 0.09, 51% had iron deficiency." (PMID 41543817, 2026). "Transferrin saturation is also the most popular way of assessing the success of iron deficiency treatment." (PMID 41753362, 2026). "Using inflammation-adjusted guideline criteria (ferritin <100 μg/L, or ferritin 100–299 μg/L with transferrin saturation <20%), iron deficiency was present in 67 of 86 patients (78%)." (PMID 41374035, 2025). "Using transferrin saturation, adjustment reduced the prevalence of functional iron deficiency on POD 3 from 95% (19/20) to 35% (7/20), reclassifying twelve patients." (PMID 41517510, 2025). "Serum iron (SI) reflects the amount of iron bound to transferrin in the circulation, which is crucial for diagnosing iron deficiency and iron-overload conditions." (PMID 41141252, 2025). "On POD 90, unadjusted measurements suggested iron deficiency in 40% of patients by serum iron measurement and 60% by transferrin saturation, whereas adjustment reduced these estimates to 15% and 35% (p = 0.063)." (PMID 41517510, 2025). "Among the patients with CKD, 40 (33%) exhibited iron deficiency, as characterized by transferrin saturation ≤ 20% and ferritin ≤ 10 μg/dl3, whereas 24 patients manifested iron deficiency anemia (21%, out of n = 114)." (PMID 40225399, 2025). "Several biochemical parameters, such as plasma ferritin and transferrin saturation, can define iron deficiency." (PMID 39804874, 2025). "In normal homeostasis and in most iron-deficiency anemia patients, serum ferritin correlates with transferrin saturation, with decreased serum ferritin reflecting reduced intracellular iron stores." (PMID 40548380, 2025). "Iron deficiency is characterized by serum ferritin levels below 100 ng/mL, signifying absolute iron deficiency, or serum ferritin levels between 100 and 299 ng/mL accompanied by transferrin saturation (TSAT) below 20%, indicating functional iron insufficiency." (PMID 40363966, 2025). "Diagnostic parameters for iron-deficiency anemia include serum iron, serum ferritin, transferrin saturation, hepcidin concentration, and the expression of its receptor, ferroportin." (PMID 40218414, 2025). "In hemodialysis patients, absolute iron deficiency is identified using transferrin saturation levels and serum ferritin measurements." (PMID 40497187, 2025). "These trials solidified that treating iron deficiency (ferritin <100 μg/L or 100–299 with transferrin saturation <20%) leads to better exercise tolerance and quality of life in HFrEF, independent of anemia status." (PMID 40910148, 2025). "In the Ptpn2-KO mouse model, the significantly reduced serum iron levels and transferrin saturation are indicative of iron deficiency." (PMID 40244226, 2025). "Iron deficiency is indicated when ferritin levels are below 100 ng/mL or between 100 and 299 ng/mL with a transferrin saturation (TSAT) of less than 20%." (PMID 39773062, 2025). "Iron-binding proteins, such as transferrin and ferritin, provide protection against free radicals; thus, iron deficiency reduces this protective effect and results in increased oxidative stress." (PMID 41268589, 2025). "Serum ferritin, total iron binding capacity, serum transferrin, transferrin saturation, and hepcidin are examples of iron-specific biomarkers that can be used to differentiate iron deficiency anaemia from other types of anaemia." (PMID 41160552, 2025).
iron deficiency (continued). "We observed high prevalence of vitamin B12 and iron deficiencies, as indicated by transferrin saturation, particularly in the 3rd trimester." (PMID 40906792, 2025). "Newer research would include more biomarkers, including hepcidin or transferrin saturation, to differentiate between iron deficiency and inflammation-induced ferritin increases in a better way." (PMID 41356605, 2025). "In this case, the patient exhibited low hemoglobin levels (10.7 g/dL) and iron deficiency (ferritin 9 ng/mL, iron 15 μg/dL, transferrin saturation 3%), indicative of iron deficiency anemia." (PMID 40416288, 2025). "Transferrin saturation was diagnostic for iron deficiency in 63 of 176 patients (35.7%) who had a normal ferritin (≥30 ng/mL)." (PMID 39564807, 2025). "ORION‐HF enrolled patients with HF and iron deficiency anaemia, which was defined as either serum ferritin concentration <100 μg/L or 100–299 μg/L with transferrin saturation concentration <20%." (PMID 40879172, 2025). "Other clinical tests, such as serum ferritin, transferrin saturation, soluble transferrin receptor, or C-reactive protein, proved to be useful adjunctive tests to assist in the diagnosis of iron deficiency." (PMID 40704327, 2025). "TTR serves as a sensitive marker of nutritional status, while transferrin levels correlate with iron deficiency, a common CD complication." (PMID 40325942, 2025). "Twelve patients aged 20-45 years with iron deficiency anemia (hemoglobin: male 8.0-13.0 g/dL, female 8.0-12.0 g/dL; serum ferritin < 12 ng/mL; transferrin saturation ≤ 16%), participated." (PMID 41239076, 2025). "Diagnosis of iron deficiency anemia relies on hemoglobin (Hb), ferritin, and transferrin saturation (TSAT) measurements." (PMID 40648893, 2025). "The 2025 KDIGO guidelines acknowledge the potential clinical benefit of iron supplementation in CKD patients with profound iron deficiency, based on specific ferritin and transferrin saturation thresholds." (PMID 40807197, 2025). "Serum ferritin and transferrin saturation are the most critical parameters for defining iron deficiency." (PMID 40637365, 2025). "Since 2016, the European Society of Cardiology (ESC) guidelines on HF recommend that physicians screen, diagnose, and treat iron deficiency, emphasizing testing for ferritin and transferrin saturation (TSAT) to identify functional iron deficiency." (PMID 40797259, 2025). "Specifically, iron deficiency was defined as a ferritin level below 100 μg/L, or between 100 and 299 μg/L if transferrin saturation (TSAT) was below 20%." (PMID 40869365, 2025). "We observed a weak association between possible iron deficiency expressed by elevated transferrin and lower FEV1 and FVC." (PMID 41029668, 2025). "Iron deficiency is generally defined as ferritin levels below 100 μg/L or ferritin levels ranging from 100 to 299 μg/L along with transferrin saturation (TSAT) below 20%." (PMID 39773062, 2025). "While a TSAT less than 20% is widely accepted as indicative of functional iron deficiency in the presence of normal ferritin, both serum iron and transferrin are influenced by inflammation and can confound interpretation." (PMID 41517510, 2025). "Under various stimuli, such as erythrocyte dilatation and iron-deficiency anemia, the transcriptional function of iron-regulated proteins is inhibited, leading to tissue hypoxia and decreased serum transferrin saturation." (PMID 40142956, 2025). "As part of the preoperative assessment, routine laboratory workup revealed microcytic hypochromic anemia (hemoglobin: 10.7 g/dL; MCV: 71.1 fL; MCH:22; ferritin: 9 ng/mL; transferrin saturation: 3%), consistent with iron deficiency anemia." (PMID 40416288, 2025). "In our study, both groups of patients showed iron deficiency and reduced transferrin levels, with significantly lower levels in the low LMR group." (PMID 41171774, 2025).
iron deficiency (continued). "According to the 2018 ESMO guidelines, ID is defined by ferritin (FTN) levels below 100 μg/L (absolute iron deficiency, AID) or FTN levels ≥100 μg/L with a transferrin saturation (TSAT) under 20% (functional iron deficiency, FID)." (PMID 41190142, 2025). "Iron supplementation (liposomal formulation is to be preferred) is indicated in case of documented iron deficiency or iron deficiency anemia or after evaluation of blood count and iron deposits: transferrin saturation (TSAT) and ferritin." (PMID 39941620, 2025). "In conclusion, this observational study in patients with HF found that 16 weeks of ferric maltol was associated with increases in haemoglobin, ferritin, and transferrin saturation, changes that indicate resolution of iron deficiency." (PMID 40879172, 2025). "In murine 3T3-L1 preadipocytes, iron deficiency—either through transferrin gene silencing or pharmacological chelation with deferoxamine—has been shown to impair adipogenesis." (PMID 41369396, 2025). "Agents that suppress hepcidin and improve transferrin saturation can address functional iron deficiency, particularly under inflammatory conditions." (PMID 41239296, 2025). "A transferrin saturation above 21% was independently associated with a reduced likelihood of severe calcification, suggesting that functional iron deficiency contributes to the development of vascular calcification in dialysis patients." (PMID 41155502, 2025). "This study investigates the prevalence of RLS among CKD patients across various treatment modalities and its association with iron deficiency using serum ferritin, transferrin saturation (TSAT), serum iron, and total iron-binding capacity (TIBC)." (PMID 40677478, 2025). "Systemic inflammation following total hip arthroplasty profoundly suppresses serum iron and transferrin saturation, leading to widespread misclassification of iron deficiency when conventional indices are applied." (PMID 41517510, 2025). "The anemia was microcytic, and predominantly due to iron deficiency based on ferritin, transferrin saturation, and blood film appearances." (PMID 40529371, 2025). "As a result, it has been suggested that the current ferritin-based definition of iron deficiency in heart failure should be replaced with a simpler, more accurate criterion focused solely on hypoferremia—defined as a transferrin saturation (TSAT) below 20%." (PMID 40869365, 2025). "Definitions of anemia were generally based on hemoglobin concentration thresholds, often aligning with WHO criteria, and some studies incorporated additional parameters such as ferritin or transferrin saturation levels to confirm iron deficiency." (PMID 40080504, 2025). "In such cases, transferrin saturation (TSAT) below 20% is widely used to identify functional iron deficiency in the presence of normal ferritin and red-cell indices." (PMID 41517510, 2025). "In these cases, transferrin saturation (TSAT) less than 20% is considered to diagnose functional iron deficiency in the presence of normal ferritin and red-cell measurements." (PMID 41517510, 2025). "Iron deficiency was established with a serum iron level of 1.2 μmol/L, transferrin level of 3.38 g/L, and serum ferritin level of 2.30 ng/ml." (PMID 39867693, 2024). "As reported by Ogun and Adeyinka, blood levels of transferrin are inversely related to body iron levels, with its production increasing in response to iron deficiency." (PMID 39600914, 2024). "Among iron- and anemia-related variables, transferrin saturation (TSAT) has been shown to be an important indicator of risk for adverse outcomes in iron deficiency." (PMID 39229929, 2024). "Clinicians ordered plasma transferrin tests for iron deficiency anemia by writing the test in the patient chart for nurse ordering (7.92%) or by choosing the test in the request forms themselves (32.7%)." (PMID 38447167, 2024).